TYR (tyrosinase)
Diseases named in the same sentence as TYR in open-access papers (continued):
Sharing a sentence is not in itself a finding about the gene and the disease.
tumor (continued). "In line with the gene expression and protein levels of E-cadherin, arguing for mesenchymal-like/undifferentiated phenotype, the amount of tyrosinase mRNA resulted significantly lower, confirming a less differentiated feature of tumor cells when compared to epithelial melanocytes." (PMID 41596411, 2026). "The rapid development of immunotherapy and targeted therapy in recent years provides a basis for the newly explored triple therapy regimen (immune checkpoint inhibitor + tyrosinase inhibitor + chemotherapy) to significantly improve tumor treatment efficacy and conversion rate." (PMID 40538855, 2025). "After validation of effective degradation of TYR and subsequent melanin decrease, we evaluated the in vivo treatment efficacy on a mouse skin hyperpigmentation model, which was established by the implementation of 1,3-dihydroxyacetone (DHA)-based self-tanning drops and UV irradiation." (PMID 40651969, 2025). "We have confirmed that these TYR-catalyzed in-situ formed PRTOACs could effectively degrade overexpressed TYR in the melanocytes and subsequently decrease the melanin levels for alleviating skin hyperpigmentation within 48 h on a mouse model." (PMID 40651969, 2025). "Thus, inhibiting tyrosinase is a promising strategy for preventing melanogenesis and skin hyperpigmentation." (PMID 40806718, 2025). "For example, the hyaluronidase enzyme regulates the hyaluronic acid degradation essential in skin hydration, while the tyrosinase enzyme is crucial for skin pigmentation; however, under oxidative stress, increased tyrosinase activity can produce skin hyperpigmentation." (PMID 39997671, 2025). "Expression of tyrosinase is also reported to increase during tumorigenesis, and it may accelerate tumor growth." (PMID 40599794, 2025). "Additionally, the allo-immunotherapy was capable of stimulating T cells directed to the tumor antigens Trp1, Trp2, gp100, and tyrosinase." (PMID 39840067, 2024). "Additionally, while tumor cells often overexpress tyrosinase and survivin, the genetic modification of the viral genome to incorporate the promoters of tyrosinase or survivin genes has been found to increase the oncospecificity of oncolytic viruses." (PMID 36769745, 2023). "We identified UM-associated hybrid cells based on co-expression of melanocytic tumor proteins: Microphthalmia-associated transcription factor (MITF), Tyrosinase (TYR), Melan-A (MLANA), premelanosome protein (PMEL, GP100), 5-hydroxytryptamine receptor 2B (HTR2B) and the pan-leukocyte marker CD45." (PMID 38106024, 2023). "Interestingly, Zhou and coworkers developed a tyrosinase (TYR)-MOF employing NPCN-333(Al) as a potent prodrug activator for cancer therapy in HeLa tumor-bearing xenograft mice by tumor-specific prodrug activation." (PMID 36593957, 2023). "The administration of autologous pDCs, activated and pulsed with tumor antigens (gp100, tyrosinase), induces a systemic type I IFN response accompanied by the migration of pDCs in draining lymph nodes and triggering of antigen-specific CD4 and CD8 T-cells in patients with metastatic melanoma." (PMID 37190135, 2023). "Additionally, we found that the melanin content and tyrosinase activity of the tumor tissues in the siRNA-Gm31932-174 treated group were significantly higher than those in the control and siRNA-NC groups." (PMID 35393397, 2022). "Namely, tyrosinase is a pivotal enzyme involved in melanogenesis within melanocytes, and as such it is a potential target molecule for the treatment of dermatological conditions accompanied by skin hyperpigmentation." (PMID 36297701, 2022). "Taken together, our findings reveal some Thai plants, along with candidate compounds as natural sources of antioxidants and potent inhibitors of elastase and tyrosinase, could be developed as promising and effective agents for skin aging therapy." (PMID 36616194, 2022).
tumor (continued). "The use of plant extracts as a source of antioxidants and tyrosinase inhibitors could be one of the therapeutic approaches for the control of problems related to skin hyperpigmentation." (PMID 36297701, 2022). "Additionally, Mentha pulegium (123.89 ± 5.64 mg KAE (kojic acid equivalents)/g) and Mentha x piperita (102.82 ± 15.16 mg KAE/g) showed a strong inhibition of the enzyme tyrosinase, which is related to skin hyperpigmentation." (PMID 33804017, 2021). "Moreover, tyrosinase expression is significantly different when the primary tumor was classified regarding the tumor size." (PMID 33396957, 2020). "Additionally, bearing in mind the complications related to DM, such as skin hyperpigmentation, the plant has also been investigated for its anti-tyrosinase property since tyrosinase enzyme is the main enzyme responsible to synthesize melanin." (PMID 33255853, 2020). "In addition, hydroxycinnamic derivatives, acting also as tyrosinase inhibitors, have found important applications in the cosmetic industry as whitening functional cosmetics in relation to skin hyperpigmentation." (PMID 31703399, 2019). "CD26+ Th17 cells isolated and expanded from TYRP transgenic mice expressing the TRP-1 T cell receptor that recognizes tyrosinase were adoptively transferred into the tumor-bearing mice, and tumor burden was measured for 128 days, during which sitagliptin treatment was constant." (PMID 30400835, 2018). "Furthermore, CHA has been proposed to inhibit tumor growth and angiogenesis by inhibiting tyrosinase and matrix metalloproteinase (MMP)-929, 30, or by the suppression of HIF-1α stabilizationand AKT phosphorylation." (PMID 28045028, 2017). "MT can reduce tyrosinase activity and melanogenesis in melanocytes, suggesting that the presence of MT prior to tumor initiation may be protective against tumor development." (PMID 29220390, 2017). "For example, accumulation of tyrosinase is around 4-fold reduced in the tumour tissue." (PMID 27432466, 2016). "Consequently the results showed that tyrosinase was only expressed in telomerase-positive tumor cells infected by hTERT-TYR, whereas tyrosinase was expressed in both telomerase-negative and telomerase-positive tumor cells infected by CMV-TYR." (PMID 27283901, 2016). "Moreover, augmented urotensin signaling in TSC or LAM tumors is consistent with the expression of other immature neural crest markers (e.g., gp100, tyrosinase), and its role in other neoplasias of neural or endocrine lineage." (PMID 27458154, 2016). "Other tumour epitopes recognised were MelanA (n = 3), tyrosinase (n = 3) and WT1126-134 (n = 1)." (PMID 26492414, 2015). "However, the IGFBP-3-induced reversion of tumor cells towards a melanocytic phenotype observed in vitro was also apparent in vivo, since tumors from treated mice appeared darker and had higher tyrosinase activity." (PMID 24905466, 2014). "Using the tyrosinase inducible system for non-tumor models (e.g., developmental biology) may reduce the level of tyrosinase expression heterogeneity seen in tumors." (PMID 24936769, 2014). "However, high variability in the levels of serum tyrosinase have been reported, most likely due to difficulties in sample processing and the transient presence of metastasizing tumor cells in the blood." (PMID 25667918, 2014). "Anti-tumor immune response targets tumor-associated antigens such as cancer testis antigens (e.g., NY-ESO-1 or MAGEs) expressed by several tumors or differentiation antigens (e.g., Melan-A/MART-1, gp100, or tyrosinase) expressed in melanoma cells." (PMID 23801991, 2013). "In this study, authors observed expression of melanocytic markers, tyrosinase and melan A, in those cells, hypothesizing that lineage infidelity had occured during tumor progression." (PMID 23599796, 2013). "Interestingly, both TRP-1 and TRP-2 showed a homogenous staining pattern, whereas the expression of gp100 and tyrosinase was restricted to certain tumor cell clusters." (PMID 24213320, 2012).
tumor (continued). "Finally, tyrosinase is a tumour antigen able to generate peptides that are presented at the cell surface in association with MHC-I." (PMID 22905195, 2012). "In addition, tyrosinase m-RNA can be used for the indirect quantification of circulating tumour cells and have been correlared with the dimensions of the primary tumour." (PMID 21773036, 2011). "Spleen cells analyzed by ELISPOT for IFNγ secretion, using immunodominant MAA peptides of tyrosinase and gp100, were found to include a much higher proportion of tumor specific T cells in tumor bearing mice treated with α-gal glycolipids than in mice with tumors injected with PBS." (PMID 23087817, 2010). "We had anticipated that the detection of peripheral blood MART1-, gp100- and tyrosinase-specific CD8+ T cells in these HLA-A2*0201+ patients might correlate with tumor regressions." (PMID 18334033, 2008). "Recent studies suggest that certain pyrazole derivatives with tyrosinase activity may also have anticancer potential by influencing melanocyte transformation and tumor progression, positioning them as promising candidates for both cosmetic and therapeutic uses." (PMID 40332760, 2025). "Moreover, specific co-expression of CXCL9 and αPD-L1 in various tumor cells is achieved by replacing the tyrosinase promoter of NPTyr-C9AP with a survivin promoter, which increases T-cell infiltration and activation and therapeutic efficacy in multiple tumors in female mice." (PMID 37031188, 2023). "In addition, differences in tumor cell metabolism, potentially due to abnormal blood perfusion, may also affect tyrosinase expression in tumor cells." (PMID 24936769, 2014). "Immunotherapy may be used for tumors because they express tumor associated antigens; melanoma lesions often contain a high number of infiltrative T-cells specific to melanocyte tumor-associated antigens such as MART1, gp100 and tyrosinase." (PMID 24899250, 2014). "Significant apoptosis in tumor cells from the Pd1-Pd2-SA@Gel group was demonstrated by TUNEL staining, suggesting effective induction of apoptotic cell death through TYR-activated prodrugs." (PMID 40651969, 2025). "Others regulate the energy metabolism, acidity, and redox balance of tumor cells, such as glucose oxidase (GOx), lactate oxidase (LOx), catalase (CAT), and tyrosinase (TYR)." (PMID 40565310, 2025). "Approximately 70% of the tyrosinase expressing GFP-positive tumor cells expressed CXCR2 in the tumors arising in Braf/Pten/CXCR2WT model and 30% of the tyrosinase expressing GFP + tumor cells in the Braf/Pten/Cxcr2−/− model continued to express CXCR2." (PMID 37270599, 2023). "Data mining the immune epitope database with the T1-116C binding consensus and validation of peptide recognition using the T2 stabilization assay identified additional tumor antigens targeted by T1-116C, including WT1, gp100, Tyrosinase and NY-ESO-1." (PMID 33836029, 2021). "Concerning UM blood samples, TYR, MLANA, and PMEL were detected in 12.5%, 4%, and 4% primary UM samples, respectively, and in 60%, 77%, and 10% tumor samples, respectively." (PMID 34885029, 2021). "TCRs targeting differentiation antigens (MART-1, tyrosinase/gp100, CEA) were mostly limited by on-target, off-tumor toxicities to healthy tissues that share antigen expression with the tumor." (PMID 32570906, 2020). "UM cells express tumor-specific antigens, including the Melanoma Antigen Gene (MAGE) family proteins, premelanosome protein gp100, and tyrosinase." (PMID 33194647, 2020). "Lymphatic vessels and B16F10Luc+ tumor cells in LNs resected from mice after 2 and 4 weeks of sponge implantation were detected by double immunolabeling for LYVE-1 and tyrosinase, respectively." (PMID 28128294, 2017). "In clinical studies, tyrosinase activity and TYRP1 expression have been shown to correlate inversely with the tumor stage." (PMID 28410220, 2017).
tumor (continued). "Of interest, one patient showing a remarkable long-term disease stabilization kept showing presence of tyrosinase specific T cells in PBMC and high infiltration of memory T cells in the tumor lesion at 21 months." (PMID 25933939, 2015). "We collected 24 tumor samples from 23 mice and analyzed the expression of MITF-M, tyrosinase, IL-1ß and miR-155 by quantitative RT-PCR using RNA extracted from total tumor tissue." (PMID 25853464, 2015). "Ethyl acetate extraction (EAE) also inhibited mushroom tyrosinase activity and significantly increased the average skin-whitening index (L value) of the skin of C57BL/6 mice, indicating its potential use for skin hyperpigmentation in humans." (PMID 25045392, 2014). "Tumor-specific tetramer+ T cell responses reached averages of 22% for MelA (range 2–60%), 0.3% for GP100 (range 0–3%), 1.2% for TYR (range 0–8%) and 0.84% for MAGE-3 (range 0–4%) in 20 days." (PMID 20454561, 2010). "Cryostat sections from 11 spindle-type, 21 mixed and epithelioid tumours and four metastasis lesions were stained with antibodies specifically recognizing gp100, MART-1, tyrosinase and TRP-1." (PMID 9820172, 1998). "This approach enabled a sharp distinction between tyrosinase‐positive and tyrosinase‐negative tumours." (PMID 41173806, 2025). "Unlike previous onco-pig models that induced tumor driver gene expression in a non-cell type-specific manner via local adenovirus delivery, our TYR enhancer/promoter-based model enables the control of oncogene expression, specifically in melanocytes." (PMID 39794352, 2025). "Furthermore, the discovery of tumor-specific CD4+ T cells, which recognize MHC II-restricted tumor antigens such as tyrosinase, CDC27, gp100, MAGE-3, Melan-A/MART-1, Eph receptor, and NY-ESO-1, underscores their importance in tumor immunity." (PMID 38887597, 2024). "More recently, an mRNA vaccine strategy using 4 non-mutated antigens, including tyrosinase, MAGE-A3, and NY-ESO-1, has induced durable objective tumor responses." (PMID 38519525, 2024). "Furthermore, melanocyte differentiation genes, including MITF, TYR, and TYRP1, were upregulated significantly by FR in class 1 relative to class 2 tumor biopsy samples." (PMID 33577798, 2021). "Our tumor vaccine may profit from incorporating other tumor antigens which are targets of cytotoxic CD8+ T cells, like the MAGE-A family, tyrosinase, NY-ESO1, gp100 or neoantigens." (PMID 30723467, 2019). "At this time point, there were no observed differences in tyrosinase expression in the spleen, regardless of host genotype or tumor injection (not shown), supporting the premise that tyrosinase expression in lungs is representative of engraftment." (PMID 28358049, 2017). "Expression of tyrosinase was detected in lungs of tumor-challenged WT mice, but tyrosinase levels in CXCR3−/− mice was not different than control (no tumor challenge) mice." (PMID 28358049, 2017). "Furthermore, tyrosinase and TYRP1 correlates inversely with tumor stage and its progression to the amelanotic phenotype." (PMID 27206672, 2016). "Tumor dimensions prior to DOX treatment varied greatly and +TYR tumor sizes were not statistically different from those of –TYR tumors." (PMID 24936769, 2014). "Tumor-specific tetramer+ CD8 T cell responses reached averages of 39% for MelA (range 12–59%), 7.4% for GP100 (range 0.2–24%), 0.3% for TYR (range 0.05–1.2%) and 1.1% for MAGE-3 (range 0.1–4.3%) after 20 days with baseline levels format day 0 1.7, 0.2, 0.05 and 0.3%, respectively." (PMID 20454561, 2010). "In the allogeneic host BALB/c (H2d) (albino mice that do not express tyrosinase), the B16 tumor was strongly rejected and purified anti-B16 antibodies from BALB/c mice were sufficient to transfer the rejection of B16 in SCID mice in an ADCC dependent way." (PMID 20672001, 2010).
tumor (continued). "The tumor-specific tetramer+ CD8 T cell responses reached averages of 23% for MelA (range 0.4–62%), 1.2% for GP100 (range 0.05–3.5%), 0.3% for TYR (range 0.01–2.5%) and 0.2% for MAGE-3 (range 0.03–0.72%) after 20 days (baseline tetramer+ CD8+ T cells ranged from 0.02 to 0.03% at d0)." (PMID 20454561, 2010). "Furthermore, in the CXCR6+ IGR37 tumor xenograft, all the MAA family proteins overlapped with the exception of CXCR6+ IGR37 cells for tyrosinase, Mart-1, and Gp100." (PMID 21203549, 2010). "We have first found that a VRP vaccine targeting TRP-2 is surprisingly effective in controlling tumor growth as opposed to vaccines based on the same viral delivery vector targeting the other melanosomal antigens, gp100 and tyrosinase." (PMID 20844763, 2010). "We first validated that TYR could catalyze the in situ generation of VHL-recruiting PROTACs to efficiently degrade TYR both in vitro and in vivo for curtailing melanin synthesis to effectively treat skin hyperpigmentation." (PMID 40651969, 2025). "However, it is highly unlikely that these neoplasms represent undifferentiated OMMs based on the absence of expression of both TYR and SOX10 RNA as well as the lack of immunolabeling for MDX and SOX-10." (PMID 34422947, 2021). "Because melastatin, a MITF transcriptional target and a putative tumour suppressor, is sharply responding to MITF levels in melanocytes 36, we used real‐time PCR to estimate the mRNA levels of melastatin, together with determining the mRNA levels of the bona fide MITF target tyrosinase." (PMID 29369499, 2018). "Importantly, sentinel LNs issued from mice implanted with gelatin sponges soaked with tumor cells for 2 weeks were negative for tyrosinase staining, revealing the absence of metastatic tumor cells." (PMID 28128294, 2017). "The mean tumor-melanin estimated concentrations were analyzed using 2-way ANOVA given that two key factors contributed to melanin induction: the presence or absence of tyrosinase and DOX treatment." (PMID 24936769, 2014). "Similarly, in agreement with previous data, tyrosinase expression was found to play an independent prognostic role in influencing DFS, together with the extension of nodal involvement and the Breslow thickness of the primary tumour." (PMID 14562017, 2003). "Unfortunately tumour specimens from recurrences were not tested for tyrosinase expression." (PMID 12107840, 2002). "Therefore, we constructed a lentiviral vector expressing tyrosinase (TYR) driven by an optimized human telomerase reverse transcriptase (hTERT) promoter or a cytomegalovirus(CMV) promoter in the hopes of performing noninvasive and real-time tumor-specific imaging." (PMID 27283901, 2016). "Therefore, if the TYR gene can be driven by specific promoters that are active in tumor cells but not in normal tissues or cells, it could be used as an MR readout for tumors." (PMID 27283901, 2016). "Immunohistochemical analysis showed positive cytoplasmic staining of the tumor cells for HMB-45, Tyrosinase, and MART1, although the expression of TTF-1 in tumor cells was negative." (PMID 26376781, 2015).